IDH2 (isocitrate dehydrogenase (NADP(+)) 2)
Diseases named in the same sentence as IDH2 in open-access papers (continued):
Sharing a sentence is not in itself a finding about the gene and the disease.
tumor (continued). "Previous studies demonstrated that the decrease level of 5 hmC in tumors was due to the reduced expression of TET1/2/3 and IDH2 genes or tumor derived IDH1 and IDH2 mutations." (PMID 23671639, 2013). "G-CIMP was also shown to be highly dependent on a mutation in IDH1 or IDH2; 99% of the tumours with a G-CIMP possessed a mutation in either of these genes and none of the tumours without a mutation was G-CIMP positive." (PMID 22771539, 2013). "These paired samples were examined for changes in phenotype, chromosomal deletions, IDH1 mutation, IDH2 mutation and methylation status of tumor-related gene promoters." (PMID 23826216, 2013). "GBM that have mutations in IDH1 or IDH2 are reported to undergo metabolic remodeling that influences the tumor survival program in response to treatment and hypoxia." (PMID 23047041, 2012). "IDH2 mutations drive metabolic reprogramming, further shaping the tumor microenvironment." (PMID 40282990, 2025). "Notably, an IDH2 or RHOA variant detected in the initial pre-treatment tumour sample was detectable in subsequent ctDNA monitoring in all of these patients following relapse." (PMID 40724970, 2025). "Over the years, it has been recognized that mutated forms of IDH1 and IDH2 may contribute to tumor development and serve as diagnostic markers." (PMID 39123479, 2024). "Moreover, it is essential to precisely dissect the mechanisms through which tumor cells are more sensitive to metabolic and epigenetic disturbances caused by IDH2 inhibition." (PMID 39409901, 2024). "This study underlines the potential contribution of IDH2 expression in macrophages and tumor microenvironment remodeling, which could be useful in clinical cancer research." (PMID 39256649, 2024). "KRAS or NRAS were mutated in six tumours (16%), and IDH1 or IDH2 were mutated in 5 tumours (14%)." (PMID 38877653, 2024). "First, IDH1 and IDH2 mutations occur in highly restricted tumor types." (PMID 38763973, 2024). "Eight separate NS mutations occurred in Idh2, with six of those (p.178Q, p.174A, p.150E, p.147V, p.138T, p.130K) occurring each once in single separate tumor and two mutations (p.176G, p.177D) each occurring in more than one tumor." (PMID 38232086, 2024). "Additionally, these tumours are defined by mutations in either IDH1 or IDH2, which is an early alteration in tumourigenesis." (PMID 37239289, 2023). "CS tumours in adults also comprise a 14q32 lesion but the transformative driver remains unknown, though some CS tumours harbour mutations in IDH1 or IDH2, which supports CS diagnosis." (PMID 36936386, 2023). "The defining molecular alterations of this tumour are missense mutations of IDH1 or IDH2, in addition to the deletion of the whole arm of chromosomes 1p and 19q, with mutations in IDH1/2 thought to be an early alteration that drives tumourigenesis prior to the establishment of 1p19q co-deletion." (PMID 37239289, 2023). "MiR-101 overexpression and IDH2 deficiency both suppressed NSCLC tumor growth in mice." (PMID 36304962, 2022). "Complex I variants were frequently present at high VAFs (mean VAF = 58.8%) with IDH2 mutation in line with co-occurrence in the same tumour clone; however, when present in IDH1-mutant samples they were at lower VAF (mean VAF = 27.3%; Wilcoxon signed-rank test P value = 0.0088)." (PMID 35551192, 2022). "However, it should be noted that the timing of the IDH1 and IDH2 mutations in the evolution of the tumour cannot be ascertained from the information at hand." (PMID 36286062, 2022). "For example, IDH2 is capable of compensating mutated IDH1 in tumor cells under hypoxic conditions." (PMID 35985423, 2022). "As it is known that 2HG exerts diverse biological functions including regulation of DNA hydroxymethylation, it is feasible that the IDH1 and IDH2 mutations explain our different methylation array findings and mediate the different behaviour of the tumour subgroups." (PMID 36042521, 2022).
tumor (continued). "As IDH1 and IDH2 mutations occur early in the evolution of the disease and appear to be retained if the tumour transforms into higher grade disease, we considered that they could be exploited as biomarkers for clinical outcome." (PMID 34528398, 2021). "The mutation of IDH1 or IDH2 leads to the elevated production of the oncometabolite 2‐hydroxyglutarate, which is thought to induce significant epigenetic alterations and promote the initiation and progression of tumor cells." (PMID 33459509, 2021). "Moreover, our biochemical data together with the previous biochemical data can explain why the cancer-associated IDH1 or IDH2 mutations cause drastic accumulation of D-2-HG in the tumor cells." (PMID 33431826, 2021). "Thus, IDH1 and IDH2 mutations represent an early event in the development of central cartilaginous tumours." (PMID 31728625, 2020). "Moreover, in the METABRIC cohort, high IDH2 mRNA levels were associated with large tumour size (p = 0.038), axillary lymph node positivity and HER2 positivity (all; p < 0.0001);." (PMID 31599393, 2020). "Furthermore, alterations in the gene expression level of IDH2, which encodes the mitochondrial isocitrate dehydrogenase, were linked to tumor growth or tumor suppression." (PMID 32640711, 2020). "As previously discussed, the patient’s tumor showed a mutation in IDH2." (PMID 26368816, 2015). "Mutations in PIK3CA, PTEN, AKT1, IDH1 and IDH2 have been reported in this class of tumours." (PMID 24867389, 2014). "Given the right context, it seems those two structurally related but different metabolites converge on a phenotype that gives an increased risk of malignancy, both in a child with an inborn error of metabolism and an adult with IDH1 or IDH2 mutations confined to the tumor." (PMID 24581008, 2014). "The product of IDH1/IDH2 mutations, d-2HG, can be detected in tumor samples." (PMID 23847760, 2013). "In addition, a study using IDH2-deficient mice revealed that IDH2 is related to tumor progression." (PMID 39256649, 2024). "Additionally, the IDH1/IDH2 mutations characteristic of ODG tumours where CIC mutations are found result in the overproduction of 2‐hydroxyglutarate (2‐HG), which has the downstream consequence of widespread hypermethylation of CpG sites and histone tail residues." (PMID 34767259, 2022). "In addition, the mutation status of IDH2 genes is associated with the prognosis of tumor patients." (PMID 33981605, 2021). "Tumor metabolism has emerged as an attractive target for therapy development, and several drugs including metformin (mitochondrial respiration), enasidenib (mutated IDH2), l-asparaginase, devimistat (PDH/αKGDH), CB-839 (glutaminase inhibitor) are being used in various cancer trials." (PMID 34911956, 2021). "Furthermore, specific tumor types show distinct predisposition to specific IDH1 or IDH2 mutations." (PMID 31727977, 2019). "Mutations on codon 132 or 172 of the IDH1 and IDH2 genes, respectively, results in “neo-enzymatic activity” with the production of the novel oncometabolite 2-hydroxyglutarate causing widespread methylation of the tumour cell DNA and altered regulation of histone methylation." (PMID 29098416, 2018). "From what has been mentioned so far, it is clear that IDH1 R132 and IDH2 R172 mutations in these types of tumor, whether they occur as early or late ones, are driver mutations and that stresses on the importance of targeting them as a candidate anticancer therapy." (PMID 28785398, 2017).
tumor (continued). "In breast cancer, SIRT5 expression is significantly elevated, and knockout of SIRT5 can induce oxidative stress by increasing the succinylation of IDH2, leading to apoptosis in tumor tissues and inhibiting tumor growth." (PMID 39944690, 2025). "A heatmap was generated to depict the expression profiles of ATRX, OLIG2, MGMT, and IDH2 in normal and tumor tissues, using Log2(TPM+1) for scaling." (PMID 40282990, 2025). "Boxplots depict the protein expression levels (Z-values) of ATRX, OLIG2, MGMT, and IDH2 in normal tissue samples (n = 10, blue) and primary tumor samples (n = 99, red)." (PMID 40282990, 2025). "Overall, mutated genes identified in the tumor‐enriched cohort were concordant, with recurrent variants identified in TET2, DNMT3A, RHOA, IDH2, and TET3." (PMID 40510016, 2025). "SIRT3 deacetylates IDH2 at K413, which activates its enzymatic activity by promoting IDH2 dimer formation, subsequently reducing intracellular ROS and glycolysis, and inhibiting the tumour‐prone phenotype." (PMID 39778006, 2025). "A significant upregulation of ATRX, OLIG2, and downregulation of IDH2 at protein level was observed in GBM tumor samples compared to normal tissues, with p-values indicating statistical significance (**** p < 0.0001; *** p < 0.001)." (PMID 40282990, 2025). "Through RT‐qPCR, IHC (scale bar, 100 μm), and western blot analysis, we observed that IDH2 expression was clearly elevated in NSCLC tumor tissues." (PMID 39113352, 2024). "All 96 tumor samples were screened for IDH1 mutations, but due to an insufficient amount of the material, only 79 were analyzed for IDH2 mutations." (PMID 38248076, 2024). "In vivo xenograft models further validated IDH2′s essential role in TNBC tumor progression, emphasizing its potential as a therapeutic target." (PMID 39409901, 2024). "For each patient, DNA was extracted and quantified from paraffin-embedded sections of tumor tissue, and the mutational status of IDH1 (codons 105 and 132) and IDH2 (codons 140 and 172) genes was assessed." (PMID 38170705, 2024). "In tumor samples, the expression of IDH2, HIF1b, HIF2a, EGRF, PTEN and STAT3 was significantly downregulated, but HIF1a and VEGFC expressions were upregulated in U87MG STAT3 KO variant in comparison with U87MG cells." (PMID 38654280, 2024). "In vivo experiments using TNBC xenograft models showed that knocking down of IDH2 severely suppressed tumor growth." (PMID 38658533, 2024). "Rescue experiments were performed to monitor the effects of miR‐758‐3p and IDH2 on tumor progression." (PMID 39113352, 2024). "We created a tumor transplantation mouse model to explore the mechanism through which IDH2 affects cancer proliferation." (PMID 39256649, 2024). "During the mature T cell phase, the emergence of tumor-specific mutations like RHOA (G17V) and IDH2 (R172) play a role in the progression of AITL." (PMID 39229263, 2024). "In contrast, inhibition of IDH2 in TNBC cells would be expected to cause a major disruption of α-KG reductive flow, a decrease in HIF1α, and a suppression of tumor growth." (PMID 38658533, 2024). "Considering the critical role of wt-IDH2 in TNBC cell survival and tumor growth and metastasis, we reasoned that pharmacological inhibition of wt-IDH2 would be effective against TNBC." (PMID 38658533, 2024). "IIDH1 and IDH2 are common mutated metabolic enzymes in cancer, and multiple studies have shown that they mutate in cancer, and mutant IDH can accelerate tumour progression, which indicates that mutant IDH is carcinogenic." (PMID 38288377, 2024). "Together, we concluded that D-mannose mediated RNF185 upregulation plays a key role in IDH2 degradation and tumor cell inhibition." (PMID 38167476, 2024). "Although it occurs recurrently in other neoplasms, such as AML and high-grade gliomas, IDH-2 mutations, when present in MTCL, are practically exclusive to AITL and are usually restricted to the arginine residue 172 (R172K and R172S)." (PMID 37182145, 2023).
tumor (continued). "There is also a positive correlation between TET1 and IDH2 in the tumor tissues of HBV-related HCC patients." (PMID 37266610, 2023). "We also detected TET1 and IDH2 were decreased in the tumor tissues and the decrease were positively correlated with the 5-hmC." (PMID 37266610, 2023). "Tumor-associated IDH1 and IDH2 mutations occur almost exclusively at different arginine residues in the active enzyme site." (PMID 37563735, 2023). "As a cancer driver gene, IDH2 can promote tumor progression via interaction between histone demethylation and hypoxia reprogramming in cancer metabolism." (PMID 35880695, 2023). "Only patients with a connotated age and a confirmed WHO grade 2 or 3 tumor with IDH1 (n = 358; 51%) or IDH2 (n = 19; 2.6%) mutations were included (n = 377)." (PMID 36648586, 2023). "Cisplatin treatment was able to delay the growth of a tumor containing wild-type IDH2 (red curve vs. black)." (PMID 36831011, 2023). "The results of Pearson correlation analysis showed that 5-hmC was negatively correlated with 5-mC and positively correlated with TET1 and IDH2 in tumor tissue." (PMID 37266610, 2023). "One group identified Isocitrate dehydrogenase 2 (NADP+) (IDH2) as a negative regulator of mitochondrial-directed tumor cell motility." (PMID 35356277, 2022). "A particular focus of our efforts was to identify mutations of relevance to patient outcome and identify recurrent driver mutations in those tumours that are wild type for IDH1 and IDH2 mutations (IDHwt)." (PMID 36042521, 2022). "In contrast, IDH2-mediated reductive carboxylation becomes critical for tumor proliferation upon hypoxia." (PMID 34764443, 2022). "In a study, the level of 2-hydroxy glutarate when checked by mass spectroscopy showed an increase in its concentration, indicating direct correlation with IDH1 and IDH2 that in turn indicates the presence of the tumor." (PMID 36185622, 2022). "Although studies have demonstrated that IDH2/HIF1α pathway was indispensable in tumor growth, the mechanism under IDH2-HIF1α regulation kept mysterious." (PMID 36304962, 2022). "While somatic mutations of IDH1 and IDH2 have been reported for several cancers, IDH3 mutations have rarely been detected in human tumours." (PMID 35744895, 2022). "It follows therefore that there is likely to be substantial overlap between the tumour cells harbouring an IDH1 and IDH2 mutation." (PMID 36286062, 2022). "Western blotting analysis of the tumor tissues confirmed a substantial decrease of IDH2 protein expression in the tumors from mice inoculated with cells harboring IDH2-shRNA." (PMID 35313945, 2022). "IDH2-mutant tumours occur in older patients and commonly present with high-grade or dedifferentiated disease." (PMID 36042521, 2022). "Analysis of mutational signatures in the 100KGP cohort (n = 52) revealed nine active signals, with SBS1, SBS5, and SBS8 being ubiquitous and most prominent across IDH1, IDH2, and IDHwt tumours." (PMID 36042521, 2022). "U937 or ML-1 cells were first infected with lentivirus carrying IDH2-shRNA or control RNA vectors and then inoculated into athymic mice to test tumor formation and growth." (PMID 35313945, 2022). "The overall methylation level across all probes also revealed significant differences between IDH1 and IDH2 tumours (p = 0.002) indicating that the former are globally hypermethylated compared to IDH2 and IDHwt tumours." (PMID 36042521, 2022).
tumor (continued). "IHC staining of tumor tissues isolated from mice inoculated with AML cells with or without IDH2 knockdown revealed a major decrease of C-MYC expression in those with IDH2 knockdown, indicating that C-MYC down regulation by IDH2 knockdown occurred in vivo." (PMID 35313945, 2022). "Here, with the benefit of large sample numbers, we have been able to study tumours with IDH1 and IDH2 mutations independently and shown that they represent distinct genetic and clinical groups." (PMID 36042521, 2022). "IDH1, IDH2 gene was a potential tumor early diagnosis, prognosis evaluation and target therapeutic marker genes." (PMID 36618415, 2022). "On the other hand, significant differences, but only for stage IV, were found for protein levels of IDH2, as the tumor showed higher protein levels compared to the non-tumor adjacent tissue." (PMID 35205159, 2022). "Immunohistochemical testing to assess the distribution of the mutant IDH1 and IDH2 proteins within the tumour was unfortunately unable to be performed, and is a limitation of our study of this case." (PMID 36286062, 2022). "Together, these data imply further differences in the rate of evolution from G2/3 to DD CS across IDH1, IDH2, and IDHwt tumours." (PMID 36042521, 2022). "The prevalence of IDH-mutations (IDH-1/IDH-2) is <5% among BTCs, while IDH-mutant tumors typically have lower tumor mutation burden (TMB) and rarely have microsatellite instability or PDL-1 positivity compared to IDH-wild type tumors." (PMID 35565266, 2022). "Applying single-cell chromatin accessibility profiling (scATAC-seq) across four primary adult GBM tumors (3797 cells), wild type for both IDH1 and IDH2, revealed seven to nine accessibility modules in each tumor based on unsupervised clustering." (PMID 33427645, 2021). "Hypoxia inducible factor-1α is a key gene for mammalian cells to adapt to hypoxia and tumor cell glycolysis dependence, and IDH2 has been found to promote Warburg effect through HIF-1α." (PMID 34513821, 2021). "In view of the important roles of mutant IDH1, IDH2 and their products in tumorigenesis and progression, another strategy of tumor therapy is to target mutant enzymes and products." (PMID 33981605, 2021). "Compared with mutational profiling routinely analyzed using tumor samples, several additional targets with currently available therapies, including IDH1, IDH2, and PDGFRA mutations, were discovered." (PMID 33816227, 2021). "Survival correlated with tumour grade, and detection of IDH1, IDH2 and GNAS mutations in plasma pre‐ and postoperatively." (PMID 34528398, 2021). "Both IDH1 and IDH2 are overexpressed in several types of tumours, decreasing ROS production and increasing concomitantly NADPH." (PMID 34880756, 2021). "Compared with mutational profiling routinely analyzed using tumor samples, several additional genomic alterations with currently available therapies were discovered, including IDH1, IDH2, and PDGFRA mutations." (PMID 33816227, 2021). "We used genome-wide DNA methylation data from CATNON trial samples and compared profiles of IDH1R132H mutated tumours (n = 369) to those harbouring other “non-R132H” IDH1 and IDH2 hotspot mutations (n = 69)." (PMID 33740099, 2021). "In this study, we aimed to assess the expression of wild-type IDH2 in BC and evaluate its role in tumour progression, particularly LVI, and patient outcome." (PMID 31599393, 2020). "IDH1 and IDH2 also catalyze the reductive carboxylation and support tumor cells growth with defective mitochondria." (PMID 33028807, 2020).